TAL1 (TAL bHLH transcription factor 1, erythroid differentiation factor)
Diseases named in the same sentence as TAL1 in open-access papers (continued):
Sharing a sentence is not in itself a finding about the gene and the disease.
hemangioblastoma (1 paper, 2023). "Our previous research showed the expression of Brachyury and TAL1 in 10 of 10 VHL-related hemangioblastomas." (PMID 37174017, 2023). "Sometimes weak, but mostly moderately strong, nuclear TAL1 expression was seen in 43 of 47 hemangioblastomas (25 cerebellar, 18 spinal), staining approximately half of the tumor area." (PMID 37174017, 2023). "TAL1 cytoplasmic expression was seen in 40 of 47 hemangioblastomas (22 cerebellar, 18 spinal), covering more than half of the tumor area." (PMID 37174017, 2023). "The presence of embryonic hemangioblast proteins (Brachyury and TAL1) has not yet been investigated in VHL-associated tumors other than hemangioblastomas." (PMID 37174017, 2023). "Similar to hemangioblastomas, tumors with nuclear Brachyury expression always co-expressed TAL1, but not vice versa." (PMID 37174017, 2023). "It was shown that the cell’s typical proteins Brachyury and TAL1 are expressed by a broader spectrum of VHL tumors rather than by hemangioblastomas only." (PMID 37174017, 2023).
idiopathic pulmonary fibrosis (1 paper, 2024). Idiopathic pulmonary fibrosis (IPF) is a nonneoplastic pulmonary disease that is characterized by the formation of scar tissue within the lungs in the absence of any known cause. "Using miloDE, we identify a transient hemogenic endothelia-like state in mouse embryos lacking Tal1 and detect distinct programs during macrophage activation in idiopathic pulmonary fibrosis." (PMID 39026254, 2024).
liver cancer (1 paper, 2019). An epithelial or non-epithelial malignant neoplasm that arises from the liver. "Finally, in invasive liver cancers, the levels of positive regulators of SERPINB2, such as TAL1 (Z-score = 3.982, p-value = 0.237), FOSL1 (Z-score = 1.483, p-value = 0.0311) and FOS (Z-score = 3.214, p-value = 0.0347), were increased." (PMID 30965654, 2019).
liver cirrhosis (1 paper, 2022). "Some of the important hub genes in the BisoGenet-derived PPI for liver cirrhosis and HCC diseases were E2F1, TAL1, CEBPB, ELF1, RAD21, CEBPB, and MYC." (PMID 35265561, 2022).
osteosarcoma (1 paper, 2021). A usually aggressive malignant bone-forming mesenchymal neoplasm, predominantly affecting adolescents and young adults. "SCL/TAL1 interrupting locus (STIL) is associated with the progression of several tumors; however, the biological role of STIL in osteosarcoma remains poorly understood." (PMID 33858425, 2021).
pancreatic cancer (1 paper, 2020). "βPix/COOL-1 has also been shown to interact with PAK1 (p21-activated kinase) and STIL (SCL/TAL1-interrupting locus), to promote actin remodelling and promote cancer cell migration in pancreatic cancer models suggesting a potential mechanism for the βPix/COOL-1 mediated invasion evident in GBM." (PMID 33256106, 2020).
Pancytopenia (1 paper, 2023). An abnormal reduction in numbers of all blood cell types (red blood cells, white blood cells, and platelets). "Post-natal heterozygous deletion of Rps12 in hematopoietic cells using Tal1-Cre-ERT also resulted in pancytopenia with decreased HSC numbers." (PMID 37272618, 2023).
paraganglioma (1 paper, 2023). A benign or malignant neoplasm arising from paraganglia located along the sympathetic or parasympathetic nerves. "In addition, this paraganglioma showed strong nuclear and moderate cytoplasmic TAL1 expression in a large area." (PMID 37174017, 2023).
Parkinson disease (1 paper, 2017). A progressive degenerative disorder of the central nervous system characterized by loss of dopamine producing neurons in the substantia nigra and the presence of Lewy bodies in the substantia nigra and locus coeruleus. "Indeed, several recent studies indicate an important role for cis-regulatory mutations in disease, not only in cancer (e.g., TERT, TAL1), but also in complex diseases (e.g., type II diabetes FTO locus, Parkinson’s disease) and in familial disorders (e.g., preaxial polydactyly)." (PMID 28854983, 2017).
pheochromocytoma (1 paper, 2023). "Weak to moderate cytoplasmic TAL1 staining was seen in seven of eight pheochromocytomas, mostly in large areas." (PMID 37174017, 2023). "Moderate to strong nuclear TAL1 staining was seen in three pheochromocytomas in a small part of the tumor area." (PMID 37174017, 2023).
renal agenesis (1 paper, 2013). Renal agenesis (RA) is a form of renal tract malformation characterized by the complete absence of development of one or both kidneys (unilateral RA or bilateral RA respectively), accompanied by absent ureter(s). "Our data indicate that Hpt is a Tal1 overexpression mutant as well, and it is interesting to note that the loss of pronephric ducts in zebrafish is consistent with the occasional finding of one-sided renal agenesis in Hpt/+ mice." (PMID 23301070, 2013).
renal cell carcinoma (1 paper, 2023). "Eleven renal cell carcinomas showed a weak to moderate cytoplasmic TAL1 expression in large tumor areas." (PMID 37174017, 2023). "Twelve of 13 renal cell carcinomas showed moderate to strong nuclear TAL1 expression, varying from small to mostly very large areas." (PMID 37174017, 2023).
Splenomegaly (1 paper, 2025). Abnormal increased size of the spleen. "Similarly, splenomegaly was most common in SIL::TAL1 patients (100%), followed by E2A::PBX1 (75%), BCR::ABL (60%), MLL::AF4 (33.3%), TEL::AML1 (30%), negative (29.7%) and unknown (25.6%)." (PMID 41234729, 2025).
Stroke (1 paper, 2018). Sudden impairment of blood flow to a part of the brain due to occlusion or rupture of an artery to the brain. "CP2, E47, IK3, TAL1, USF, and YY1 are TF that has not been previously shown to be associated with stroke." (PMID 29856744, 2018).
cancer (44 papers, 2009 to 2025). A tumor composed of atypical neoplastic, often pleomorphic cells that invade other tissues. "The MSigDB Cancer Neighborhood highlighted cancer-associated genes, TAL1, ANK1, SPTB, SPTA1, PRDX2, MAP2K3, etc.." (PMID 25522020, 2014). "In this review, we look more closely at the TERT promoter and TAL1 enhancer alterations and use these examples to ask whether other cis-regulatory mutations may play a role in cancer susceptibility." (PMID 26356674, 2015). "The identification of the recurrent TERT and TAL1 mutations raises the possibility that other cis-regulatory regions may acquire somatic mutations that contribute to cancer by similar mechanisms." (PMID 26356674, 2015). "SCL/TAL1 interrupting locus (STIL) regulates centriole replication and causes chromosome instability, which is closely related to malignant tumors." (PMID 36497260, 2022). "Emerging evidence shows that cancer cells can acquire super-enhancers in the vicinity of key oncogenes, such as MYC and TAL1, during the development of cancer." (PMID 35300417, 2022). "Allele-specific targeting of enCRISPRa to oncogenic TAL1 super-enhancer modulates TAL1 expression and cancer progression in xenotransplants." (PMID 31980609, 2020). "SCL/TAL1 interrupting locus (STIL) regulates the mitotic centrosome to promote the centriolar replication and cell cycling, and is associated with malignancies." (PMID 31187582, 2019). "Unexpectedly, three cancer related-pathways genes (Tal1, PPAR-γ, and RXRA) were identified as hub genes in neonates." (PMID 31456798, 2019). "After validating μ-cisTarget on the TAL1, LMO1, and TERT mutations, we analyzed ten widely used cancer cell lines as a discovery set." (PMID 28854983, 2017). "We find that somatic mutations create or disrupt putative miRNA target sites in the 3′UTRs of many genes, including several genes, such as MITF, EPHA3, TAL1, SCG3, and GSDMA, which have been previously associated with cancer." (PMID 23091610, 2012). "For example, increased expression of TAL1, SCG3 and GSDMA has been observed in cancers, and somatic mutations in the 3′UTRs of these genes disrupt putative targets of miRNAs that have been associated with cancer." (PMID 23091610, 2012). "We observed similar cancer-specific H3K4me3-BDs associated with hijacking of super-enhancers of other common oncogenes in B cell (MAF, MYC, and FGFR3/NSD2) and T cell malignancies (LMO2, TLX3, and TAL1)." (PMID 34933939, 2022). "TAL1 (T-cell acute lymphocytic leukemia protein 1) is a basic-helix-loop-helix (bHLH) TF, an essential regulator of normal hematopoiesis, and also a winning downregulated TF in three types of cancer." (PMID 36101460, 2022). "We postulate that disturbance of the regulatory loop between TAL1 and the miR-17-92 cluster could be an important step in cancer development and progression." (PMID 33293632, 2020). "We identified non-coding hotspots upstream of three known T-ALL oncogenes (LMO1, LMO2, and TAL1), demonstrating that hotspot detection could be useful even in small cancer cohorts." (PMID 32550006, 2020). "In addition, this polymorphism affects binding to 5 proteins implicated in cancer development (CCNT2, GATA2, TAL1, KAP1 and CTCF)." (PMID 27437873, 2016). "Also of potential relevance to the regulation of TAL1 by microRNAs in the context of T-ALL is the knowledge that mRNA transcripts in cancer cells frequently display shorter 3′UTRs then those in normal cells." (PMID 26882564, 2016). "However, despite scientifically rigorous analyses of WGS data from a range of cancers, non-coding somatic mutations have yet to be identified with such robust links to cancer development as the TERT and TAL1 regulatory examples." (PMID 26356674, 2015). "In various types of cancers, SEs control the expression of prominent tumor-promoting genes such as MYC, TAL1, STAT3 and EGFR, and mediate transcription dysregulation of cancer cells." (PMID 38254188, 2024).
cancer (continued). "SCL/TAL1 interrupting locus (STIL) promotes proliferation, invasion, and cancer progression by regulating the expression of CDK1, CCNB2, CDC20, CCNA2, BUB1, and AURKB." (PMID 36661515, 2023). "During cancer development, cancer cells can acquire super-enhancers near key oncogenes, such as MYC and TAL1, and several oncogenic super-enhancers have been found across a broad spectrum of cancers." (PMID 36147741, 2022). "The downregulated projected network had 62 known regulatory interactions, of which transcription factors TAL1, ZEB1 and MEIS1 regulate the genes which were differentially regulated in more than half of the cancers studied." (PMID 34728699, 2021). "Comparing with pan-cancer driver genes, our study found that SIX1 was up-regulated, while TAL1 and ID4 were down-regulated in NSCLC." (PMID 31681566, 2019). "We found that SPARCL1, ENG, TAL1, ATP8A2 and HOXA9 were down-regulated in 99, 94, 89, 65 and 49% of the 82 cancer samples." (PMID 28178989, 2017). "Many of the genes, identified in this study as the potential targets of differentially regulated miRNAs are known to be involved in cancer through their effects on cell differentiation (CDK6, LIFR), apoptosis (PIM1) or hematopoiesis (GATA2, TAL1)." (PMID 20459673, 2010). "This patient’s karyotype and presentation of Y;1, with no known cancer, suggest no aberrant activation of TAL1 when translocated into the Y chromosome." (PMID 40761946, 2025). "Among these 16 negative-specific TMM genes, only FGFR3 and TAL1 were cataloged by the curated Cancer Gene Census." (PMID 35953846, 2022). "We used three GSC cultures and glioma resections to examine the expression, regulation, and role of two transcription factors, SLUG (SNAI2) and TAL1 (SCL), involved in epithelial to mesenchymal transition (EMT), hematopoiesis, vascular identity, and treatment resistance in various cancers." (PMID 34771555, 2021). "The gene expression levels of SPARCL1 and TAL1 were down-regulated in all the eight cancer tissues compared with their paired adjacent normal tissues, while ENG was down-regulated in six of the eight cancer tissues." (PMID 28178989, 2017). "Additionally, Hu et al18 found that CPEB4 was strongly induced by the important erythroid-related transcription factors Gata1 and Tal1 and that 1 CPEB4 target gene is CDK6, an important protein in cell cycle regulation and cancer development." (PMID 26166131, 2015). "In addition, of all the 31 Onco/TSGs harboured sHyperMethyl and sHypoMethyl in their gene body, 7 genes (HOXD11, TAL1, HOXA9, PAX5, FOXP1, FOXO1, TERT) were reported to serve as potential DNA methylation-based biomarkers for non-invasive early cancer diagnosis." (PMID 37393582, 2023). "The upregulated DEGs showed various enforced transcription factors’ networks including IRF3, TAL1, JUN, and FOXA, whereas the downregulated DEGs demonstrated dramatic network suppression of E2F1, a cell cycle progressor, and NR2C2, a cancer-promoting orphan receptor." (PMID 37612293, 2023). "An increased cellular level of CK2 as such is not sufficient to provoke a cancer phenotype, but it has been shown in a mouse model that cooperation of the overexpressed enzyme with other oncogenes, such as myc or tal-1 can essentially promote cancer development." (PMID 29462988, 2018). "Thus, it is well worth to examine if TAL1 or FUBP1 contribute to aberrant proliferation and differentiation in cancers, in which no obvious alterations in the loci of cell cycle and differentiation regulators themselves can be detected." (PMID 30653565, 2019). "In addition, several of these genes have not previously been reported as methylated in any type of cancer (KCNK4, SEPT5, PENK, BMP4, TAL1, PGF, SMARCB1 (INI1), FRZB (SFRP3), IRAK3 and MCM2)." (PMID 19493342, 2009).
tumor (44 papers, 2009 to 2025). "The effect of SAM to decrease methylation was proved to be beneficial in certain genes (HT-29: DTX1, GATA4, SEZ6L, TP53INP1; SW480: HAAO, TAL1), whose hypermethylation was associated with tumor progression according to the scientific literature." (PMID 32784836, 2020). "Multiple genetic drivers of T-ALL, including activating mutations in NOTCH1, deletion of the CDKN2A tumor suppressor locus, and aberrant expression of transcription factors, such as T-cell acute lymphocytic leukemia 1 (TAL1) and LIM domain only 2 (LMO2), have been identified." (PMID 37805579, 2023). "Importantly, upon xenotransplantation into immunodeficient NSG (NOD-scid IL2Rgnull) mice, enCRISPRa-mediated TAL1 enhancer activation led to greater tumor burden with significantly increased bioluminescence signals of the luciferase-expressing T-ALL cells in mice 4 weeks post transplantation." (PMID 31980609, 2020). "MiR-146b-5p is another tumor suppressor whose expression is negatively regulated by transcription factor TAL1, leading to enhanced migration and invasion in vitro and lower overall survival in mouse models." (PMID 36982511, 2023). "For instance, miR-101, which is frequently downregulated in primary T-ALL samples, plays a tumor-suppressor role, as it suppresses the expression of Notch1 and the proto-oncogene TAL1." (PMID 36982511, 2023). "For example, in xenografts, the enCRISPRa allele was precisely localized to a carcinogenic TAL1 SE and shown to govern TAL1 expression and tumor growth." (PMID 37501079, 2023). "In three of five tumors, moderately strong nuclear TAL1 staining was observed in a larger population of tumor cells." (PMID 37174017, 2023). "Our analysis suggests a regulatory role for TAL1 in controlling tumor morphology, particularly tumor variance." (PMID 36902378, 2023). "The possible involvement of TAL1 in regulating tumor immune infiltration was first reported in the present study." (PMID 34489925, 2021). "SLUG and TAL1 are expressed in the tumor microenvironment by perivascular and endothelial cells, respectively, and to a minor extent, by a fraction of epidermal growth factor receptor (EGFR) -amplified GBM cells." (PMID 34771555, 2021). "Disruption of the transcriptional complex involving TAL1 would efficiently block the formation of the CRC and revert the functional imbalance between oncogenic TAL1 complex and E-protein tumor suppressors." (PMID 29034206, 2017). "Tal1 expression, undetectable in quiescent mature endothelium, occurs in forming vessels, including vascular proliferations and tumor lymphatic vessels." (PMID 22792348, 2012). "While TAL1 and its partners are considered promising therapeutic targets in the treatment of T-ALL, our results show that TAL1-short could act as a tumor suppressor and suggest that altering TAL1 isoform’s ratio could be a preferred therapeutic approach." (PMID 37379322, 2023). "TAL1 is frequently downregulated in LUAD because it may be silenced by hypermethylated CpG sites within its promoter region, supporting TAL1 as a potential tumor suppressor of LUAD." (PMID 37826914, 2023). "In other words, these miRNAs would have a tumor suppressor-like role by keeping in check TAL1." (PMID 26882564, 2016). "The cluster miR-17-92 is highly up-regulated in hematopoietic malignancies and has a clearly defined oncogenic function, which was not consistent with our hypothesis that the candidate miRs should act as tumor suppressor-like genes (by down-regulating TAL1)." (PMID 26882564, 2016). "In T-ALL, the transcription factors TAL1, GATA3, and RUNX1 form a positively connected self-regulatory loop that regulates T-cell homeostasis and directly activates MYB to facilitate tumor progression." (PMID 40083704, 2025). "Our study unveiled the synergistic effect of USP7 haploinsufficiency with aberrant TAL1 activation on T-ALL, implicating USP7 as a haploinsufficient tumor suppressor in T-ALL." (PMID 33664368, 2021).
tumor (continued). "For example, it not only acts as tumor suppressor in certain T-ALL cases 32, but KDM6A overexpression in TAL1-expressing T-ALL increasesd their growth." (PMID 33456567, 2021). "Suppression of UTX in several TAL1-positive cell lines result in an increase in apoptosis, whereas overexpression of UTX enhances tumor cell proliferation." (PMID 34465286, 2021). "In our work, we showed that TAL1 is a direct target of miR-101 in T-ALL cell lines, in accordance with studies indicating a possible tumor suppressor role of miR-101 has in hematological malignancies." (PMID 26882564, 2016). "For instance, in LSCC we observed four TFs (HOXA4, HOXA5, TAL1, ZNF132) undergoing promoter hypermethylation in at least 50 % of the LSCC tumour samples where these TFs were underexpressed." (PMID 27562343, 2016). "Some endothelial cells showed cytoplasmic staining with TAL1 (but not in all tumors), usually in larger vessels with plump endothelial cells, and sometimes large vascular structures surrounded by tumor cells." (PMID 37174017, 2023). "Sometimes, weak to strong cytoplasmic Brachyury and TAL1 staining was seen in some, but not all, endothelial cells that were contained by positive nuclear or cytoplasmic tumor areas, and sometimes in negative areas." (PMID 37174017, 2023). "Finally, we examined in detail the expression of TAL1 and SLUG in the tumor microenvironment and tumoral cells." (PMID 34771555, 2021). "While MAP17 levels are typically increased in tumor samples compared to levels in non-tumoral samples, no changes in the expression of TAL1 have been observed, showing that, at least in cancer cells, MAP17 transcription is independent." (PMID 29650022, 2018). "The identification of TAL1, LMO2 and LYL1 as new critical regulators of ANG-2 expression definitively establishes the important role of these factors in endothelial cells, and more particularly in tumor angiogenesis and development." (PMID 22792348, 2012). "Brachyury and/or TAL1 staining was never seen in the whole tumor cell population." (PMID 37174017, 2023). "TAL1 is a member of the basic helix-loop-helix family of transcription factors and its downregulation could suppress the activity of the tumor suppressor TGF-β in the early phase of tumor through downregulating KDR expression." (PMID 28178989, 2017).